C3orf80 (chromosome 3 open reading frame 80)
Tractability: Antibody: UniProt predicts a signal peptide or a membrane-spanning region.
Gene: Protein-coding gene on chromosome 3 (160,225,422 to 160,228,213, forward strand). Ensembl gene ENSG00000180044.
Subcellular location: Membrane
Gene Ontology:
Cellular component: membrane
Genetic constraint (gnomAD): Loss-of-function variants: 10 observed, 9.21 expected, observed/expected ratio (o/e) 1.09, 90% interval 0.67 to 1.75. That is too few expected variants to judge how well the gene tolerates losing a copy. Missense variants: 364 observed, 254.27 expected, observed/expected ratio (o/e) 1.43, 90% interval 1.31 to 1.56. Synonymous variants: 183 observed, 125.96 expected, observed/expected ratio (o/e) 1.45, 90% interval 1.29 to 1.64.
Homologues: Orthologues: macaque C2H3orf80 (99% identical), rat C2h3orf80 (92% identical), mouse 1110032F04Rik (91% identical), pig C3orf80 (91% identical), chimpanzee C3H3orf80 (82% identical), dog C3orf80 (81% identical), tropical clawed frog c5h3orf80 (44% identical).